HORMAD1 (HORMA domain containing 1)
Diseases named in the same sentence as HORMAD1 in open-access papers (continued):
Sharing a sentence is not in itself a finding about the gene and the disease.
lung carcinoma (5 papers, 2018 to 2024). "However, the precise role of HORMAD1 in lung cancer growth and progression and the potential underlying mechanism has not been investigated." (PMID 35347116, 2022). "However, the detailed biological functions of HORMAD1 in lung cancer progression and the underlying mechanisms remain unknown." (PMID 35347116, 2022). "However, the role and underlying regulatory mechanisms of HORMAD1 in lung cancer progression remain unknown." (PMID 35347116, 2022). "An opposite function of HORMAD1 was described in lung cancer, where HORMAD1 has been shown to promote DNA damage repair in response to ionizing radiation and camptothecin, and in TNBC cell lines treated by docetaxel, where HORMAD1 knockdown enhanced apoptosis." (PMID 36852691, 2023). "HORMAD1 aberrant expression is reported in lung cancers, TNBC, ovarian cancers, and gastric cancers." (PMID 36852691, 2023). "Our results provide new insights into the functional role and regulatory mechanism of HORMAD1 in lung cancer progression and identify HORMAD1 as a promising prognostic biomarker and therapeutic target for lung cancer." (PMID 35347116, 2022). "We revealed a new oncoprotein expression profile of HORMAD1 in lung cancer and demonstrated that HORMAD1 is significantly upregulated in lung cancer, and that its overexpression is associated with poor prognosis." (PMID 35347116, 2022). "Taken together, our study reveals that HORMAD1 functions as a novel regulator of the Wnt/β-catenin signaling pathway in lung cancer progression." (PMID 35347116, 2022). "Collectively, our results suggest that aberrantly overexpressed HORMAD1 leads to lung cancer growth and metastasis by acting as a oncogenic regulator." (PMID 35347116, 2022). "Aberrant HORMAD1 expression stimulates the metastatic properties of lung cancer cells by promoting EMT." (PMID 35347116, 2022). "To investigate the tumorigenic potential of HORMAD1 in lung cancer cells, we stably overexpressed HORMAD1 in HORMAD1-negative H157 cells and knocked out HORMAD1 in HORMAD1-positive H650 cells using two independent guide RNAs." (PMID 35347116, 2022). "Collectively, these results demonstrate that HORMAD1 promotes lung cancer cell EMT and motility through the Wnt/β-catenin pathway." (PMID 35347116, 2022). "We further demonstrate that HORMAD1 promotes the proliferation, migration and invasion of lung cancer cells both in vitro and in vivo by inducing epithelial–mesenchymal transition (EMT)." (PMID 35347116, 2022). "Collectively, these data suggest that HORMAD1 promotes the migration and invasion of lung cancer cells in vitro." (PMID 35347116, 2022). "The migration and invasion abilities of H157 lung cancer cells were significantly increased after HORMAD1 overexpression, and those of H650 cells were significantly decreased after HORMAD1 KO." (PMID 35347116, 2022). "In conclusion, we revealed that HORMAD1 functions as an oncogenic marker to promote lung cancer growth and metastasis." (PMID 35347116, 2022). "In lung cancer, HORMAD1 promotes homologous recombination to mitigate DNA damage and protect stalled replication forks from excessive MRE1-mediated nucleolytic degradation, while loss of HORMAD1 significantly reduces tumor growth in vivo and enhances sensitivity to irradiation and PARP inhibition." (PMID 38596293, 2024). "Given that regulation of β-catenin protein level is the key feature of Wnt/β-catenin pathway, we sought to determine whether HORMAD1 affects the β-catenin protein level in lung cancer cells." (PMID 35347116, 2022). "Given that HORMAD1 promoted the migration and invasion of lung cancer cells, we hypothesized that HORMAD1 might stimulate lung cancer metastasis by regulating EMT." (PMID 35347116, 2022). "This study is the first to show the function and mechanism of HORMAD1 in lung cancer progression." (PMID 35347116, 2022). "For the first time, our study revealed that aberrantly expressed HORMAD1 may function as an EMT inducer to promote lung cancer metastasis." (PMID 35347116, 2022).
lung carcinoma (continued). "The opposite effects were observed in HORMAD1 KO lung cancer cells." (PMID 35347116, 2022). "We then investigated whether HORMAD1 promotes lung cancer cell migration and invasion by regulating EMT." (PMID 35347116, 2022). "Moreover, we reveal that HORMAD1 promotes the proliferation, migration, and invasion of lung cancer cells both in vitro and vivo." (PMID 35347116, 2022). "In addition, we revealed the signaling mechanism by which HORMAD1 regulates the Wnt/β-catenin in lung cancer cells." (PMID 35347116, 2022). "Therefore, the HORMAD1-induced malignant phenotypes of lung cancer cells correlate with activation of the Wnt/β-catenin pathway." (PMID 35347116, 2022). "In addition, we demonstrate that HORMAD1 activates the Wnt/β-catenin pathway to induce EMT during lung cancer metastasis by regulating AKT/GSK-3β signaling." (PMID 35347116, 2022). "However, no study has yet attempted to investigate functional participation of HORMAD1 in lung cancer metastasis." (PMID 35347116, 2022). "Therefore, HORMAD1 promotes DSB repair in lung cancer cells but suppresses DSB repair in the germ line." (PMID 30333500, 2018). "This study provides new insights into the protumorigenic role of HORMAD1 and the regulatory mechanism by which it regulates the Wnt/β-catenin pathway in lung cancer progression and indicates that HORMAD1 may be a potential therapeutic target for lung cancer." (PMID 35347116, 2022). "Our results herein demonstrated that overexpression of HORMAD1 significantly increased the expression of ZEB-1, N-cadherin, and Vimentin and decreased the expression of E-cadherin in lung cancer cells." (PMID 35347116, 2022). "The Cell Counting Kit-8 assay demonstrated that HORMAD1 overexpression significantly promoted the growth of HORMAD1-negative H157 lung cancer cells, whereas HORMAD1 KO markedly compromised the growth of HORMAD1-expressing H650 lung cancer cells." (PMID 35347116, 2022). "Moreover, HORMAD1-mediated regulation of EMT-related markers was eliminated by ZEB-1 knockdown, suggesting that ZEB1 is required for HORMAD1-induced EMT process in lung cancer cells." (PMID 35347116, 2022). "Furthermore, the Wnt inhibitor XAV939 impairs HORMAD1 overexpression-induced lung cancer cell motility and EMT, and this effect can be reversed by the Wnt activator CHIR99021 in HORMAD1 knockout (KO) cells." (PMID 35347116, 2022). "In this study, we report that HORMAD1 is significantly upregulated in lung cancer tissues compared with the paired noncancerous tissues and that HORMAD1 overexpression predicts poor prognosis in patients." (PMID 35347116, 2022). "To further investigate whether HORMAD1 promotes EMT and metastatic behaviors in lung cancer cells via the Wnt/β-catenin pathway, we treated H157-HORMAD1 and H650-HORMAD1 KO cells with the Wnt/β-catenin signaling specific inhibitor XAV939 or activator CHIR99021, respectively." (PMID 35347116, 2022). "Given that HORMAD1 increased the expression of ZEB-1, but not Snail1 or Slug, we hypothesized that HORMAD1 promotes EMT in lung cancer cells by increasing the expression of ZEB-1." (PMID 35347116, 2022). "Interestingly, HORMAD1 (but not any of the other CTA tested) was redistributed to IRIF and co-localized with γH2AX in irradiated H1299 lung carcinoma cells." (PMID 30333500, 2018).
ovarian carcinoma (4 papers, 2020 to 2024). A malignant neoplasm originating from the surface ovarian epithelium. "HORMAD1 expression increased HR efficiency in HORMAD1-negative ovarian cancer cell line OVCAR5, while HORMAD1 KO decreased HR efficiency in HORMAD1-expressing ovarian cancer cell line MDAH2774." (PMID 32647118, 2020). "Paclitaxel‐induced apoptosis is enhanced when the expression of HORMAD1, also known as CT46, is disrupted by ovarian cancer cells." (PMID 38896069, 2024). "Since only 4.85% of the OV samples (15 out of 309 samples) had distinct high levels of HORMAD1 expression, we further examined HOMRAD1 expression in ovarian cancer cell lines." (PMID 32647118, 2020).
Infertility (3 papers, 2010 to 2020). "Inactivation of HORMAD1 results in infertility due to failure in pairing and synapsis of chromosomes, however, the number of oocytes was not affected suggesting that HORMAD1 is part of a synapsis checkpoint." (PMID 33287328, 2020). "The biological processes significantly represented among differentially expressed genes included mitochondrial function (Mrps31 and Trit1), cell senescence (Gpx6, Lamtor1 and Hist1h1e), cell growth (Hormad1 and Hormad2), infertility (Sycp3), and embryo development (Gli3)." (PMID 29851234, 2018). "Infertility in Hormad1−/− females is due to early embryo demise." (PMID 21079677, 2010).
Obesity (3 papers, 2017 to 2021). Accumulation of substantial excess body fat. "Additionally, other causal genes are highly expressed or known to act in human brain function (i.e., NEGR1, GNPDA2, CYP46A1, DGKH) and various carcinomas (i.e., PMAIP1, HORMAD1, FES, BCAS3), indicating the potential role of metabolic dysregulation in the pathogenesis of obesity and cardiac events." (PMID 33910581, 2021).
breast tumors (2 papers, 2018 to 2024). "We then focus on the two genes whose expression is most highly associated with basal breast tumors: HORMAD1 and CT83." (PMID 38467851, 2024). "We then use machine learning to identify the two Cancer/Testis genes most associated with basal-like breast tumors: HORMAD1 and CT83." (PMID 38467851, 2024). "These genes have only been studied individually so far, however compelling evidence suggests that HORMAD1 overexpression impairs homologous recombination and increases genetic instability in basal breast tumor cells, possibly speeding up tumor evolution." (PMID 38467851, 2024). "The two best predictors, HORMAD1 and CT83, are strongly associated with basal breast tumors: of the 190 basal-like breast tumors, 89% expressed either HORMAD1 or CT83, compared to only 13% of Her2-amplified, 6% of Luminal B, and 2% of Luminal A tumors." (PMID 38467851, 2024). "To begin uncovering the role of HORMAD1 and CT83 expression in basal-like breast tumors, we first wanted to understand how this aberrant expression becomes induced." (PMID 38467851, 2024). "These bioinformatic analyses provide clear evidence that, of the various C/T genes identified, HORMAD1 and CT83 are the most compelling as potential biomarkers for basal-like breast tumors due to their basal tumor-specific expression." (PMID 38467851, 2024). "These promoters overlap the ATAC-seq peaks which are present in HORMAD1/CT83-expressing basal-like breast tumors, but absent in non-expressing tumors." (PMID 38467851, 2024). "Overexpression of HORMAD1 was detected in 52.2% of TNBC breast tumors but not in any of the ER-positive tumors." (PMID 30046392, 2018).
melanoma (2 papers, 2013 to 2024). A malignant, usually aggressive tumor composed of atypical, neoplastic melanocytes. "Genes in cluster 8 (GSTO2, LRRC34), 9 (CLPTM1L) and 10 (CTSS, SETDB1, ANXA9, GOLPH3L, HORMAD1, PPIL3, CASP9, ALS2CR12) underlie the association between melanoma and cancers." (PMID 38308491, 2024). "Both SPO11 and HORMAD1 have been specifically noted in melanoma and we found them to be overexpressed in melanoma compared to nontransformed cell types using western blot analysis and immunofluorescence." (PMID 23840955, 2013). "Melanomas have also been shown to express meiosis specific proteins including SCP1 (homologous chromosome pairing), HORMAD1 (meiotic synapse regulation), SPO11 (double stranded DNA breaks), and REC8 (meiosis cohesion protein)." (PMID 23840955, 2013).
squamous cell carcinoma (2 papers, 2023 to 2025). A carcinoma arising from squamous epithelial cells. "We studied the relationship between the expression of the meiosis protein HORMAD1 and genomic instability in squamous cell carcinomas (SCCs)." (PMID 37371097, 2023).
teratoma (2 papers, 2014 to 2016). A non-seminomatous germ cell tumor characterized by the presence of various tissues which correspond to the different germinal layers (endoderm, mesoderm, and ectoderm). "In this study two genes were identified, Hormad1 and Zg16, as abnormally expressed in iPSCs-teratoma but not in ES-teratoma, being directly responsible for the immunogenicity of iPSCs derivatives." (PMID 26805822, 2016). "Two genes, zymogen granule protein 16 (Zg16) and Hormad1, which were expressed in regressing iPS cell teratomas but not in ES cell teratomas, were reported to contribute to iPS cell immunogenicity." (PMID 25166861, 2014).
breast adenocarcinoma (1 paper, 2018). "In addition, the HCC1806 cell line is an acantholytic squamous cancer, not breast adenocarcinoma, which may explain its resistance to rucaparib treatment irrespective of HORMAD1 overexpression." (PMID 30046392, 2018).
colorectal cancer (1 paper, 2016). A primary or metastatic malignant neoplasm that affects the colon or rectum. "Other candidates, PARG and TDGF1, have been associated with cancer regulation; however, the functional role of the candidates HORMAD1, PIGC, NCAM2, INO80D, SLCO2A1, SLC12A1, and METTL19 was unclear in colorectal cancer." (PMID 27383761, 2016).
male fertility (1 paper, 2019). A fertility quality of inhering in a male by virtue of the bearer's disposition to initiate, sustain, or support reproduction. "In humans, HORMAD1 has also been proposed to be important for male fertility, based on the finding of three SNPs found in human male patients diagnosed with infertility." (PMID 31719618, 2019).
metastatic prostate carcinoma (1 paper, 2022). A carcinoma that arises from the prostate gland and has spread to other anatomic sites. "It demonstrates a tightly associated sub-network of the meiotic cell cycle with strictly meiosis-specific (i.e., HORMAD1, MND1, SMC1B) genes and includes CT genes such as TTK and PBK (known also for metastatic prostate carcinoma)." (PMID 36499258, 2022).
ovarian failure (1 paper, 2010). "In contrast to other critical genes during meiosis, such as Dmc1, Msh5, Spo11 and Atm that cause early ovarian failure due to rapid loss of oocytes following disruption of meiosis I, Hormad1 deficiency does not activate apoptotic pathways and does not lead to gross premature loss of oocytes." (PMID 21079677, 2010).
testicular germ cell tumor (1 paper, 2020). A germ cell tumor arising from the testis. "Indeed, HORMAD1 expression was low in most normal samples of different tissue origins, but was high in most samples in testicular germ cell tumors (TCGT)." (PMID 32647118, 2020).
cancer (24 papers, 2013 to 2025). A tumor composed of atypical neoplastic, often pleomorphic cells that invade other tissues. "While many Cancer/Testis genes are repressed by DNA methylation, HORMAD1 and CT83 are highly specific in their association with basal tumors." (PMID 38467851, 2024). "Aberrant HORMAD1 expression in cancer cells has been shown to be associated with genomic instability and DNA damage repair pathway regulation." (PMID 35347116, 2022). "When illegitimately expressed in human cancers, HORMAD1 expression is associated with elevated genomic instability." (PMID 35768547, 2022). "HORMAD1 expression is also associated with an increased mutation load and genomic instability in a human cancer samples cohort from the TCGA dataset." (PMID 35251135, 2022). "Since replication stress is a hallmark of cancers, it is likely that cancers has a unique environment so that replication stress couples with HORMAD1-mediated compromised DNA mismatch repair to increase mutation load in HORMAD1-positive cancers." (PMID 32647118, 2020). "Consistently, HORMAD1 expression is associated with increased mutation load and genomic instability in many cancers." (PMID 32647118, 2020). "Significant positive correlations between HORMAD1 expression and various genomic instability features were identified in 8 out of 12 group I cancers, suggesting that HORMAD1 expression is indeed associated with genomic instability in many cancers." (PMID 32647118, 2020). "Consistent with the idea that elevated mutation load leads to the generation of neoantigens that binds MHC proteins and induces antitumor adaptive immunity, HORMAD1 expression was associated with increased neoantigen counts in these cancers." (PMID 32647118, 2020). "Since HORMAD1 compromises DNA mismatch repair, an important component in the maintenance of genomic stability, it is possible that HORMAD1 expression is commonly associated with genomic instability in cancers." (PMID 32647118, 2020). "Our immunoblot analysis of HORMAD1 expression in a panel of cancer cells identified several HORMAD1-positive and HORMAD1-deficient cell lines." (PMID 30333500, 2018). "HORMAD1 is the best studied of these meiotic cancer genes and it is well established that HORMAD1 expression correlates with an increase in mutation burden, neo-antigen production, and gross chromosomal abnormalities in cancer." (PMID 37838177, 2023). "Despite this inconsistency, which may reflect the effects of HORMAD1 depletion on cell cycle in differing contexts, it is clear from multiple studies that HORMAD1 expression in cancer positively associates with increased genomic instability and poor prognosis." (PMID 35768547, 2022). "Since HORMAD1 compromises DNA mismatch repair and HORMAD1 is associated with increased mutation load and increased neoantigen counts in several cancers, it is possible that HORMAD1-expressing cancers can respond to immune checkpoint blockade therapy." (PMID 32647118, 2020). "Additional factors might trigger the mutation load increase in cancers after HORMAD1 expression as well (see “Discussion” section)." (PMID 32647118, 2020). "The interaction between HORMAD1 and MCM8–MCM9 complex suggest that the function of HORMAD1 in cancer cells might be linked with MCM8–MCM9 complex." (PMID 32647118, 2020). "Interestingly, HORMAD1 expression was associated with increased tumor mutation load in several cancers." (PMID 32647118, 2020). "Moreover, the HORMA Domain Containing 1 (HORMAD1) protein has been linked to genomic instability in cancer." (PMID 27275820, 2016). "Therefore, the drastic difference in the duration of HORMAD1 expression (weeks vs. years) might underline the mutation load difference between cells and cancers." (PMID 32647118, 2020). "Interestingly, our analyses reveal that HORMAD1 expression is associated with increased mutation load and increased neoantigen counts in several cancers, which indicates that additional factors trigger the generation of mutations in these cancers." (PMID 32647118, 2020).